CXCL10 (C-X-C motif chemokine ligand 10)
Diseases named in the same sentence as CXCL10 in open-access papers (continued):
Sharing a sentence is not in itself a finding about the gene and the disease.
gout (6 papers, 2016 to 2025). A condition characterized by painful swelling of the joints, which is caused by deposition of urate crystals. "CXCL10 rates were overexpressed in synovial fluid of PsA versus gout or SpA, but rates were similar to those of RA." (PMID 36532039, 2022). "CXCL10 was tenfold greater (p = 0.007) in patients with PsA than in patients with OA and 36.2-fold greater than in patients with gout (p = 2.6 × 10-6)." (PMID 27964744, 2016). "In SF, CXCL10 and IL-17A mRNA and protein levels are higher in patients with PsA than in those with OA or gout and similar to those of patients with RA." (PMID 27964744, 2016). "We also observed higher mRNA levels of the Th17-specific transcription factor RORγt (RORC) in PsA SF than in OA, gout, and RA SF, supporting the involvement of Th17 and a possible link with CXCL10 in PsA." (PMID 27964744, 2016). "Indeed, increased levels of CXCL8 (IL-8), CXCL1 (KC) and CXCL10 (IP-10) have been detected in synovial fluid in patients with gouty arthritis." (PMID 27863506, 2016). "This suggests that CXCL10 may play analogous roles in patients with PsA and patients with RA, but it may distinguish patients with PsA from those with OA and gout." (PMID 27964744, 2016). "In fact, drugs targeting CXCL10 may be a new therapeutic approach for acute gouty arthritis." (PMID 33519292, 2020). "CXCL10 may have an important etiological role in PsA that is analogous to that in RA, and it is a candidate biomarker to distinguish PsA from healthy individuals and from patients with OA and gout." (PMID 27964744, 2016). "Although the inhibitory effect of SSG on Il-1β, Ifn-γ, and Cxcl10 was weaker than that of canakinumab, SSG more effectively promoted the release of anti-inflammatory factors compared to classic treatments of gout." (PMID 40417211, 2025). "In our present study, expression levels of CXCL10 and CXCR3 were found to be elevated in SF of patients with PsA as compared with patients with OA and those with gout." (PMID 27964744, 2016). "CXCL10 levels (median 5.39 ng/ml, IQR 1.81–9.82 ng/ml) were significantly elevated in PsA compared with OA (median 0.83 ng/ml, IQR 0.73–3.38 ng/ml; p = 6 × 10−4) and gout (median 0.97 ng/ml, IQR 0.80–1.48 ng/ml; p = 0.004)." (PMID 27964744, 2016). "Indeed, similar to what we saw in CXCL10 and CXCR3 levels, we observed that mRNA expression and protein levels of IL-17A were comparable between PsA and RA samples, in accordance with reports in the literature, and significantly higher than in OA and gout SF samples." (PMID 27964744, 2016). "CXCL10, IL-17A, and TBX21 expression were elevated in SF cells of patients with PsA compared with those of patients with OA and gout, but not those of patients with RA." (PMID 27964744, 2016).
Hepatic steatosis (6 papers, 2015 to 2025). Steatosis is a term used to denote lipid accumulation within hepatocytes. "p38α-deficiency in macrophages resulted in attenuated hepatic steatosis, due to reduced secretion of pro-inflammatory cytokines (TNF-α, CXCL10 and IL-6)." (PMID 36845555, 2023). "WT and CXCL10−/− mice on the FFC diet had similar increase in hepatic steatosis and triglyceride content." (PMID 27349927, 2016). "Expression levels of C-C chemokine receptor 1 (CCR1) and chemokine (C-X-C motif) ligands 9, 10, 14 (CXCL9, CXCL10, and CXCL14) are increased in livers during HFD-induced hepatic steatosis." (PMID 25887406, 2015). "We made similar observations in our study regarding the protective effect of CXCL10−/− against liver injury and fibrosis; although, in our current study, we did not observe a difference in hepatic steatosis and TG content between the FFC-fed CXCL10−/− and WT mice." (PMID 27349927, 2016).
lichen planus (6 papers, 2017 to 2025). A chronic, recurrent, pruritic inflammatory disorder of unknown etiology that affects the skin and mucus membranes. "EGCG reduces C-X-C motif chemokine ligands (CXCL10) and myxovirus resistance protein 1 staining intensity in epidermis equivalents and CXCL10 secretion by keratinocytes upon stimulation, demonstrating potential for local treatment of lichen planus." (PMID 39204235, 2024). "Similar changes in gene expression have been described in the skin of lichen planus patients in which we detected the distinct expression of CXCL10 in keratinocytes near the border to invading T cells." (PMID 31447864, 2019). "In lichen planus patients who show a massive T cell infiltration into the skin we detected the expression of CXCL10 in keratinocytes near the invasion front." (PMID 31447864, 2019). "It has been theorized ALDY is closely related to lichen planus (LP) and other lichenoid dermatologic conditions that are involved with the interferon (IFN) γ/CXCL10 pathway." (PMID 41211346, 2025).
liver failure (6 papers, 2013 to 2021). A liver disease characterized by the liver losing or has lost all of its function. "The multivariate analysis confirmed both cytokines as independent predictors of liver failure [IL-6: HR 1.43 (1.09–1.88), p = 0.01; CXCL10: 1.5 (1–2.24), p = 0.05] and liver recipient survival [IL-6: HR 1.36 (1.06–1.75), p = 0.016; CXCL10: 1.45 (1–2.1), p = 0.052]." (PMID 33758270, 2021). "Trends for a higher percentage of primary non-function as cause of liver failure, and a higher percentage of graft failure as cause of liver recipient death were evident, especially when the high IL-6/CXCL10 category was analysed." (PMID 33758270, 2021).
Myelopathy (6 papers, 2013 to 2026). Myelopathy is an descriptive term, referring to pathology leading to a neurologic deficit related to the spinal cord. "When compared with healthy controls, the presence of myelopathy in AMN patients was reflected by significantly altered blood levels of CXCL10 (478.4 [344.7–730.1] pg/mL vs 258.8 [186.3–435.9] pg/mL, adj." (PMID 37683329, 2023). "We discuss current evidence of CAR-T-associated myelopathy, its proposed inflammatory and immune-trafficking mechanisms, and the potential contribution of interleukins and chemokines such as IL-1, IL-6, IL-18, CCL-2 and CXCL10 signaling to spinal cord injury." (PMID 41993175, 2026).
Neonatal sepsis (6 papers, 2011 to 2025). Systemic inflammatory response to infection in newborn babies. "In summary, transcriptomic profiling has uncovered key immune pathways involved in neonatal sepsis, including T-cell receptor signaling (CD3G), leukocyte chemotaxis (CXCL10, CSK), inflammatory activation (MM8, NF-κB1A), and IFN-1-mediated immune modulation." (PMID 40927580, 2025).
pneumonitis (6 papers, 2007 to 2024). An inflammatory process affecting the lung parenchyma. "Importantly, the late induction of CXCL10 was associated with immune cell infiltration, pneumonitis, and alveolar damage." (PMID 34205098, 2021). "Monocyte chemoattractant protein-1 (MCP-1)/CCL2 and interferon-inducible protein-10 (IP-10)/CXCL10 have been reported to be involved in the process of sialadenitis and pneumonitis in MRL/lpr mice." (PMID 17284325, 2007).
pulmonary hypertension (6 papers, 2019 to 2025). Increased pressure within the pulmonary circulation due to lung or heart disorder. "Indeed, CXCL10 has an established association in the pathophysiology of pulmonary hypertension (PH) where it is shown to be raised in the plasma of (IPAH) patients and also correlates with BNP and right ventricular dysfunction." (PMID 41034322, 2025). "Inhibition of CXCL10 in animal models have been shown to improve pulmonary hypertension and LPS-induced lung injury." (PMID 38481391, 2023).
schistosomiasis (6 papers, 2012 to 2025). An infectious disease caused by parasitic trematodes of the genus Schistosoma that colonize human blood vessels and release eggs that can cause granulomatous reactions leading to acute (swimmer's itch or acute schistosomiasis syndrome) or chronic disease. "HSCs can also be activated during the chronic stage of schistosomiasis, and in turn, they can produce chemokines like CCL2, CCL3, and CXCL-10 following liver injury." (PMID 35839247, 2022). "Individuals from schistosomiasis-endemic regions exhibit higher levels of CXCL10 and CXCL9 compared to non-infected individuals." (PMID 41476985, 2025). "After bio-function analysis, we focused on two chemokines CXCL9 and CXCL10, and showed that both of them can inhibit the expression of collagen in human HSCs line LX-2, liver non-parenchymal cells, and primary HSCs of schistosomiasis mice indicating the anti-fibrosis property." (PMID 22905138, 2012). "In vitro, we demonstrated that CXCL9 and CXCL10 inhibited the expression of collagen, TGF-β and TIMP1 of hepatic non-parenchymal cells of mice infected with S. japonicum, while increased the gene expression of MMP9, suggesting that they played an anti-fibrosis role in the liver of schistosomiasis." (PMID 22905138, 2012). "The results showed that CXCL9 and CXCL10, but not CXCL11 or CXCL4, significantly inhibited the gene expressions of Col1α1, Col3α1 and α-SMA, indicating the potential anti-fibrosis effect of CXCL9 and CXCL10 in schistosomiasis." (PMID 22905138, 2012).
systemic inflammatory response syndrome (6 papers, 2010 to 2025). SIRS is a serious condition related to systemic inflammation, organ dysfunction, and organ failure. "Remarkably, CCL2 and CXCL10, both of which are increased in patients developing a systemic inflammatory response syndrome following SARS-CoV-2 infections, showed a strong hypoxic induction upon subsequent infection with SARS-CoV-2." (PMID 37377965, 2023). "In this regard, Tat-Tg mice were more susceptible to the systemic inflammatory response syndrome caused by the intra-peritoneal injection of LPS, based on the evidence of increased lethality and expression levels of TNF-α, IL-1α, IL-6 and CXCL10 in the peritoneal lavages of surviving animals." (PMID 26343909, 2015).
Thrombocytopenia (6 papers, 2021 to 2024). A reduction in the number of circulating thrombocytes. "In PMF patients, CXCL8 is associated with leukocytosis, and CXCL10 levels correlate with thrombocytopenia." (PMID 34084749, 2021). "Severe thrombocytopenia was positively correlated with IL-4, CXCL10, IL-6, IL-10 and IFN-γ levels, renal dysfunction was related to an increase in IL-2, IL-1β, IL-17A and IL-8, and hepatic impairment with CXCL10, MCP-1, IL-6 and IFN-γ." (PMID 36178979, 2022). "These analyses showed that IL-4, CXCL10 and IFN-γ levels were significantly higher in patients with severe thrombocytopenia or with hypoglycemia." (PMID 36178979, 2022). "Thrombocytopenia and hypoglycemia were the most characteristic manifestations in the severe P. vivax malaria group, having a shared pro-inflammatory cytokine/chemokine profile (IFN-γ, IL4, IL6 and CXCL10)." (PMID 36178979, 2022).
Acute hepatitis (5 papers, 2020 to 2023). Acute hepatic injury resulting from inflammation typically accompanied by increased serum alanine transaminase activity. "Similar results have only been found in one acute hepatitis study, where CXCL9, CXCL10, CXCL11 and CXCL13 elevated during the acute phase but then decreased in conjunction with an HBsAg decline." (PMID 36304473, 2022).
acute lymphoblastic leukemia (5 papers, 2015 to 2025). Leukemia with an acute onset, characterized by the presence of lymphoblasts in the bone marrow and the peripheral blood. "HSPC secreted factors, such as CXCL10 have not been evaluated in the setting of drug resistance in AML, but have been suggested to promote chemoresistance and blast migration to the BM of an acute lymphoblastic leukemia model." (PMID 38228679, 2024).
airway hyperresponsiveness (5 papers, 2011 to 2025). "It is reported that a number of chemokines such as CCL2, CCL5, CXCL10 are associated with RSV-induced airway hyperresponsiveness and CCL11, CCL17, and CCL 22 are involved in the development of pulmonary eosinophilia with RSV infection." (PMID 21980478, 2011). "In RSV-infected mice, antibody-mediated neutralization of CXCL10 resulted in increased airway hyperresponsiveness and heightened expression of mucus genes, decreased the number and maturation of dendritic cells, and reduced CD8+ T cells specific to RSV." (PMID 39403383, 2024). "DiABZI administration during HDM challenge increased airway hyperresponsiveness, neutrophil recruitment with prominent NOS2+ARG1− type 1 neutrophils, protein extravasation, cell death by PANoptosis, NETs formation, extracellular dsDNA release, DNA sensors activation, IFNγ, IL‐6 and CXCL10 release." (PMID 39466641, 2025).
aneurysm (5 papers, 2009 to 2022). Bulging or ballooning in an area of an artery secondary to arterial wall weakening. "Furthermore, differences were observed in inflammation between types of aneurysms, since CXCL10 is expressed 20-fold higher in AAA compared to popliteal artery aneurysms (PAA)." (PMID 24868552, 2014). "Confirming this protective role for Th1 cytokines, it was recently shown that absence of both IFNγ or its downstream chemokine CXCL10 also ameliorate aneurysm development." (PMID 19582157, 2009).
bacterial pneumonia (5 papers, 2018 to 2025). Acute infection of the lung parenchyma caused by bacteria (e.g., Streptococcus pneumoniae, Haemophilus influenzae, Chlamydia pneumoniae, Mycoplasma pneumoniae, and Legionella pneumophila). "We determined CXCL10 plasma levels in samples from 20 TB patients, 11 patients with bacterial pneumonia, and 12 healthy controls." (PMID 30026741, 2018). "The CCL18, CXCL9, CXCL10, CXCL11, and MMP9 levels were also elevated in patients with other respiratory diseases, such as bacterial pneumonia and COPD." (PMID 40269953, 2025).
brain injury (5 papers, 2014 to 2025). Acute and chronic (see also brain INJURIES, CHRONIC) injuries to the brain, including the cerebral hemispheres, CEREBELLUM, and brain STEM. "Neopterin and CXCL-10 in CSF are locally produced in the CNS and are elevated in cases of brain trauma or CNS infections, such as neuroarboviroses, neuroCOVID-19, and HAM." (PMID 39861878, 2025). "The expression of chemokines (e.g., CCL2, CCL5, CXCL10, and CXCL13) was also elevated in peripheral blood after brain injury and strongly associated with poor prognosis of TBI patients." (PMID 37208955, 2023).
celiac disease (5 papers, 2014 to 2025). An autoimmune genetic disorder with an unknown pattern of inheritance that primarily affects the digestive tract. "CXCL9 and CXCL10 are key regulators of T cell trafficking, and elevated CXCL10 promotes T cell recruitment in celiac disease." (PMID 31481960, 2019). "Especially, the gluten-specific CD4+ T cells are known to express CXCR3, responding to the CXCL9 and CXCL10 that are expressed in the coeliac regions, for which CXCL9 and CXCR are suggested as the therapeutic targets for the coeliac disease." (PMID 39897058, 2025). "Similar to celiac disease, expression levels of GBP5, CXCL10, IFI27, and IFNG were increased in tissues of patients with no or low-grade intestinal injury." (PMID 36282455, 2023).
Cerebral ischemia (5 papers, 2014 to 2025). Restriction of arterial blood supply to the brain associated with insufficient oxygenation to support the metabolic requirements of the tissue. "It has also been observed that CXCL10 might exacerbate blood–brain barrier damage caused by NK cells during cerebral ischemia." (PMID 38861234, 2025). "STAT3 activation has been associated with increased neuroinflammation in cerebral ischemia, of which found that the JAK2-STAT3 pathway was involved in the LCN2 induction of CXCL10 secretion and possibly other phenotypic changes associated with reactive astrogliosis." (PMID 29867513, 2018). "Postmortem studies on animals and humans have demonstrated that cerebral ischemia initiates the expression of various chemokine classes in the brain, such as CCL2, CCL3, CCL5, CXCL8, CXCL10, and CXCL12." (PMID 38861234, 2025).
cholestasis (5 papers, 2018 to 2025). Impairment of the bile flow caused by obstruction within the liver, or outside the liver in the bile duct system. "In addition, C-X-C motif chemokine ligand 10 (CXCL10) was also elevated in cholestasis group." (PMID 38951890, 2024). "In the Mdr2−/− murine model of cholestasis, there was increased IFN-γ, CXCL10, and hepatic macrophages with elevated CCL2." (PMID 39859319, 2025).
chronic pancreatitis (5 papers, 2014 to 2021). A chronic inflammatory process causing damage and fibrosis of the pancreatic parenchyma. "Significantly higher levels of CXCL10 and CXCR3 are observed in PAAD specimens compared to those from chronic pancreatitis." (PMID 33681290, 2021).
cryptococcal infection (5 papers, 2017 to 2025). "When comparing the cytokines that these cells are capable of producing with the cytokines known to be induced by cryptococcal infections in the brain, a small list is generated: CXCL10, IL6, CCL5, and IFN-γ." (PMID 40985448, 2025). "Moreover, CXCL10, which was specifically induced in monkey lung tissues, was shown to be abundantly expressed in patients with cryptococcosis." (PMID 31329596, 2019).
delirium (5 papers, 2013 to 2025). A disorder characterized by confusion; inattentiveness; disorientation; illusions; hallucinations; agitation; and in some instances autonomic nervous system overactivity. "In our research, we found higher levels of CXCL8, CXCL9, and CXCL10 to be associated with delirium in univariate analysis." (PMID 38861234, 2025). "Univariate analysis revealed that elevated levels of CXCL10, CXCL9, and CXCL8 were linked to an increased delirium risk." (PMID 38861234, 2025). "IL-6, IL-8, IL-10, IL-18, TNF-α, and chemokines (CCL2, CCL3, CXCL1, and CXCL10) have also been reported to be elevated in ICU delirium patients and are associated with delirium severity." (PMID 39308447, 2024). "In univariate analysis, increased levels of CXCL8, CXCL9, and CXCL10 showed an association with delirium, although this link was not evident in the multivariate analysis." (PMID 38861234, 2025). "However, there are no data whether delirium is associated with M1 macrophage, Th1, Th2, Th17, Treg or CIRS cytokine profiles, and whether a neurotoxic cytokine profile including M1, Th1, Th17 and neurotoxic chemokines, such as CCL11, CCL2, CCL3, CCL5, and CXCL10) is associated with delirium." (PMID 35641947, 2022).
encephalomyelitis (5 papers, 2015 to 2023). Inflammation of the brain and the spinal cord. "We also showed increase of tumour necrosis factor, IL-6 and CXCL10 in the transcriptomic analysis, which were also found in the cerebrospinal fluids of EV-A71 encephalomyelitis patients." (PMID 28724943, 2017). "Importantly, analysis of autopsied neural tissues from humans with WNV encephalomyelitis revealed upregulation of CXCL10-coding gene and symptom development was positively correlated with CXCL10/IP-10 production during the earliest phase of disease." (PMID 36992514, 2023). "Major histocompatibility complex (MHC) II-dependent antigen presentation, CXCL10- and CCL2-mediated recruitment of T cells and macrophages, respectively, are required for fibrinogen-induced encephalomyelitis." (PMID 26353940, 2015). "CXCL10 is involved in the generation of parasite-specific CD8 T-cell-mediated immune responses, and CXCL10 expression in the central nervous system regulates antibody-secreting cell accumulation during SARS-CoV-2-induced encephalomyelitis." (PMID 37998327, 2023).